CD4 (CD4 molecule)
Diseases named in the same sentence as CD4 in open-access papers (continued):
Sharing a sentence is not in itself a finding about the gene and the disease.
tumor (continued). "In the lymph nodes, orally administered β-glucan activate DCs which capture dying tumor cells in vivo in the tumor setting and activate antigen-specific CD4 and CD8+ T-cells." (PMID 31344853, 2019). "While these studies showed that CD8+ CD4 CAR T cells were cytotoxic against CD4+ tumor cell lines, the most effective ratio of CD4 to CD8 T cells for adoptive transfer remains the subject of ongoing investigation." (PMID 30891427, 2019). "PD-L1 blockade induced selectively the expansion of tumor-infiltrating CD4+ and CD8+ T-cell subsets, co-expressing both activating (ICOS) and inhibitory (LAG-3, PD-1) molecules." (PMID 31412943, 2019). "CD4+ T cells are considered to contribute to anti-viral and anti-tumor immune responses by producing cytokines that activate CD8+ T cells and B cells." (PMID 31507621, 2019). "CD4-positive TILs are predominantly TH cells localized within the tumor stroma, and CD8-positive TILs are cytotoxic T lymphocytes (CTLs) that infiltrate both the tumor stroma and adenoma/CRC epithelium." (PMID 31637216, 2019). "We then analysed the expression profile of CD4+ T-cell subtypes, which are commonly modulated in tumours." (PMID 31409774, 2019). "They play a crucial role in immune evasion, immunomodulation, and impairment of effector immunity and believed to be emerged to change the balance of the immune system, importantly CD4+ T cells in the chronic inflamed tumor site." (PMID 31024835, 2019). "The percentage of CD4+FOXP3+ Treg cells from the tumor infiltrating lymphocytes (TILs) of CRC patients was obviously higher than that from paired PBMCs." (PMID 31395078, 2019). "In conclusion, this study provides a high-resolution characterization of tumor-reactive CD4+ T cell responses in lymphoid organs and the TME." (PMID 31801070, 2019). "An increase in T-cells CD4 memory resting and neutrophils infiltrating and surrounding the tumor burden was observed in our cohort of AYA-RMS compared to PEDS-RMS, suggesting AYA-RMS have a compromised/suppressed immune profile." (PMID 31533233, 2019). "Because IL-35 has been described to limit anti-tumour immunresponses, we next analysed CD4 mRNA expression in a larger cohort of patients with NSCLC." (PMID 30956278, 2019). "α-PD-1 monotherapy skews the CD4 + T cell balance in favor of immunosuppressive Tregs, and elevate pSmad3 signaling within tumor cells, features that are blocked by α-TGFβ therapy." (PMID 30832732, 2019). "In particular, CD4+ T lymphocytes contribute to immune evasion and facilitate tumor growth, whereas CD8+ T lymphocytes have a defective cytotoxic potential." (PMID 30816121, 2019). "Recently, cancer immunotherapy aims to elicit the activity of CTLs within a tumor, strengthening the helper CD4+ T cells function can improve the efficiency of antitumor activity of CTLs, clonal expansion, and providing effector and memory CTL." (PMID 31024835, 2019). "Tumor-associated macrophages induce a more immunosuppressive phenotype, leading to an enhanced expression of TIM-3 and PD-1 on CD4+ and CD8+ T cells." (PMID 31641355, 2019). "The density of CD3+CD4+ T cells in the tumor decreased in six of seven patients receiving 1.0 mg/kg IT1208, while case 10 with PR showed a dramatic increase in the density of both CD3+CD8+ and CD3+CD4+ T cells in the tumor area." (PMID 31340866, 2019). "After 48 hours of culture with Raji or JeKo-1 tumor cells and CD20xCD3 bsAb, both CD4+ and CD8+ T cells were highly proliferative, as indicated by increased expression of Ki-67." (PMID 31882897, 2019). "From studies in both mice and humans, it is becoming more appreciated that the efficacy of anti-tumor responses is enhanced by the generation of both CD4+ and CD8+ “memory-like” T cell compartments." (PMID 31379821, 2019). "Now, we are in the process of conducting phase I clinical trial of a humanized anti-human CD4 depleting antibody IT1208 in Japan to promote the anti-tumor effect in human." (PMID 30696484, 2019).
tumor (continued). "The ratio CD4+FOXP3C+ Tregs/CD8+ T cells rises when the tumor contains also B7H4+ TAMs, leading to decreased cancer lysis and poorer outcome." (PMID 31096567, 2019). "Compared to the other anti-mCTLA-4 sensitive models, JA-2011 displayed a different pattern of tumor-infiltrating leukocyte populations, with a low infiltration of lymphocytic CD4+ and CD8+ effector cells, and many neutrophils." (PMID 30791458, 2019). "Since CD4+ T helper cells also play an important role in the tumor elimination e.g., by increasing the cytotoxic function of CD8+ cells and secretion of IL-2, several studies investigated them as a potential prognostic factor." (PMID 31554169, 2019). "The optimal polarization of CD4+ T cells is essential to obtain durable systemic anti-tumour immunity." (PMID 31519961, 2019). "The infiltration of CD4+ Treg cells into solid tumors can decrease the anti-tumor activity of CD28-CD3ζ signaling CART cells." (PMID 31835562, 2019). "This triple combination therapy improved T cell effector function in tumor bearing mice by increasing the proportion of tumor infiltrating CD4+ and CD8+ T cells that can produce both interferon gamma and TNF." (PMID 31052546, 2019). "CD4+ T lymphocytes were primed with EVs isolated from DCs expressing HER2/Neu or HER2 tumor antigens ex vivo and used as anti-tumor immunotherapeutic vaccines." (PMID 31680949, 2019). "Although cytotoxic CD8+ CART cells, in particular, mediate direct tumor cell eradication, CD4+ T helper cells (Th cells) were identified as a highly potent and clinically important T cell subset." (PMID 31835562, 2019). "α-PD-1 therapy enhances CD4 + Treg/CD4 + Th ratios and increases tumor cell pSmad3 expression in CCK168 SCCs, whereas α-TGFβ antibody administration attenuates these effects." (PMID 30832732, 2019). "Alternatively, a conventional naïve CD4+ T cell may encounter a tumor-associated (‘self’) or tumor-specific (‘neo’) antigen in the tumor environment, become activated, and under the influence of an immunosuppressive tumor microenvironment, differentiate into an induced FOXP3+ (‘iTreg’)." (PMID 31635338, 2019). "Such CD4+ cells were found in the tumor and draining lymph node (dLN) of MC38-GP tumor-bearing mice but in neither non-draining LN (nLN) from MC38-GP mice nor mice carrying control MC38 tumors." (PMID 31801070, 2019). "We identify previously unrecognized transcriptomic patterns among tumor-specific T cells and provide an extensive mapping of the CD4+ T cell immune response against cancer." (PMID 31801070, 2019). "Consecutive production of cytokine IL-1β stimulates CD4+ T lymphocytes to produce IL-17 which in turn accelerates tumor growth." (PMID 31555270, 2019). "Immunohistochemical analysis of the ABn on-treatment tumor samples revealed significant enrichment of CD4+ T helper cells and CD8+ cytotoxic T cells." (PMID 30728358, 2019). "This evidence emphasizes the critical role of CD4 T cells in promoting the cross-priming of tumor-specific CD8 T cells." (PMID 31221199, 2019). "The TAI subset of CD4+ T cells was also significantly more abundant, representing about 17% of the total CD4+ T-cell population within the tumor infiltrated immune cells of the treated group compared to 8% in the control group." (PMID 31412943, 2019). "The primary tumor treated with CPMV and its combinations contained more CD4+ T cells than the distant tumor, suggesting CPMV can directly recruit CD4+ T cells into the tumor microenvironment." (PMID 31453050, 2019). "The average percentages of CD4+CD25−Dx5+ cells in tumor-free, in tumor-bearing PEF2 and PEF2 + Ca-treated mice were 9.5%, 15%, 10.2% and 12.4%, respectively." (PMID 31717542, 2019). "We found that the Macrophages M0, T cell CD4 memory resting and Macrophages M2 were among the highest-proportion immune cells across all the sixteen tumor types." (PMID 31074374, 2019).
tumor (continued). "Intriguingly, tumor CD4+CD8+ double positive T cells were remarkably accumulated in response to CAH (+), accounting for 21.00 ± 7.08% of all T cells." (PMID 30886812, 2019). "We have demonstrated that ablation of Treg cells in advanced primary tumors induces a strong anti-tumor response, which is dependent on CD4+ T cells and IFNγ." (PMID 31555258, 2019). "Oral administration of A. muciniphila with FMT of non-responder feces restored the antitumor effect of anti-PD-1 mAb through the accumulation of CCR9+ CXCR3+ CD4+ T lymphocytes in mouse tumor beds." (PMID 31718585, 2019). "We demonstrate that α-PD-1 therapy results in skewing of the CD4+ Teff/Treg balance in favor of immunosuppressive Tregs, and these Tregs functionally limit the anti-tumor activity of α-PD-1 in CCK168 SCCs." (PMID 30832732, 2019). "Low concentration of IL-24 inhibited CD4+ T cell proliferation and dampened tumor-infiltrating Th1 response." (PMID 31921658, 2019). "In contrast, tumor-bearing mice with high C5a-producing cancer cells have an accelerated tumor progression with less CD4+ and CD8+ T cells in the tumor, tumor-draining lymph nodes, and the spleen." (PMID 31031765, 2019). "Taken together, these results suggest that tritherapy increases CD8+ T-cell cytolytic activity and enhances CD4+ T-cell cytokine production in the tumor." (PMID 31747946, 2019). "The proportion of T cells CD4 memory resting was significantly different among four tumor stages of cancer." (PMID 31681739, 2019). "Fourteen days after i.v. tumour inoculation, disseminated tumour growth induced an increase of Tregs (Foxp3+CD25+ cells gated on CD4+) in the spleen from 6.8 ± 1.7% in naïve mice to 18.8 ± 3.6% in tumour-bearing mice." (PMID 31683642, 2019). "Increasing numbers of S-100+ DCs infiltrating tumor epithelium correlated with higher numbers of intraepithelial CD4+ and CD8+ T cells." (PMID 30984181, 2019). "A single dose of LDC depleted CD4+CD25+ T regulatory cells in tumor bearing animals, and significantly increased the effects of subsequent immunotherapy." (PMID 31683667, 2019). "Previously, the participation of Cx43 channels as functional structures of immunological synapses formed among DCs and CD4+ T cells, between DCs and NK cells, and among NK cells and target tumor cells has been described." (PMID 31547237, 2019). "Consistently, reduced tumour growth in vivo was associated with enhanced tumour infiltration by CD8+ effector T cells, with an increase in the CD8+/CD4+ T-cell ratio." (PMID 31350404, 2019). "Analysis of the immune cells at the tumor site and in peripheral blood 30 days post injection, revealed that IRF7 silencing caused an increase in Gr1+CD11b+ cells and a decrease in CD4+, CD8+ T and B lymphocytes in both models." (PMID 30546090, 2019). "Here, we show that at the time of the first treatment decision, FL patients with a high tumor burden exhibit low percentage of naive CD4+ and CD8+ T cells." (PMID 31530876, 2019). "The number of CD8+ TILs was inversely correlated with tumor grade, whereas the number of CD4+ TILs was positively correlated with tumor grade." (PMID 30857299, 2019). "Effective anti-tumor activity is dependent upon CD4+ T cells, which orchestrate many immunological pathways that ultimately lead to effector activation." (PMID 31694167, 2019). "Construction of an optimal vaccine against tumors relies on the availability of appropriate tumor-specific antigens capable to stimulate CD4+ T helper cells (TH) and CD8+ cytolytic T cells (CTL)." (PMID 31417570, 2019). "Tumor specific CD4+ T cells have a broad activity beyond the provision of helper signals to CD8+ T cells." (PMID 31555274, 2019). "Our analyses dissect the complexity of the CD4+ T cell response to tumor antigens and identify broad transcriptomic divergences between anti-tumor and both acute and chronic anti-viral responses." (PMID 31801070, 2019).
tumor (continued). "EMT tumor cells also induced the generation of immunosuppressive regulatory DCs (DCreg), which induced immunosuppressive CD4+Foxp3+ Tregs and eventually impaired the induction of antitumor CTLs." (PMID 31096701, 2019). "Noteworthy, CD4+ T cells are critical for expansion, trafficking and functioning of cytotoxic CD8+ and memory T cells, an effect known as “CD4+ T-cell help” fostering tumor destruction through cytokine signaling, especially IFN-γ and TNF-α." (PMID 31812953, 2019). "Tumor necrosis should release high amounts of tumor-derived antigens to be taken up by APCs and promote CD4+T cell activation and an enhanced antitumor response." (PMID 31366386, 2019). "CD8+, CD4+ T cells, and Treg cells exhibited a gradual upregulation of IC-molecules the closer they were to the tumor." (PMID 31801611, 2019). "FOXP1 works as a negative regulator of tumor-specific CD4+ T helper 7 (Th7) cells for cancer immunotherapy, since mature naïve CD4+ T cells proliferate to exert antitumor effect programmed by IL-7 only in the absence of FOXP1." (PMID 31815635, 2019). "To study the CD4+ T cell response to tumor antigens, we aimed to produce genome-wide single-cell mRNA expression profiles (scRNA-seq) in CD4+ TILs and CD4+ dLN cells." (PMID 31801070, 2019). "In RIP1‐Tag5 tumours, which were devoid of immune infiltrates, treatment with TNFα‐CSG (5 daily i.v. injections of 2 or 5 μg) caused a significant influx of CD8+ and CD4+ T cells and macrophages." (PMID 31709774, 2019). "Studies have shown that tumor-derived TGF-β significantly inhibits the proliferation of human CD4+ T cells activated by dendritic cells." (PMID 31195692, 2019). "Ovarian cancer-induced IRE1-XBP1-dependent ER stress results in impaired glucose import and metabolism in CD4+ T cells, thereby allowing tumor progression." (PMID 31535086, 2019). "Patients with functional CD4 immunity and PD‐L1 tumor positivity exhibited response rates of 70%, highlighting the contribution of CD4 immunity for efficacious PD‐L1/PD‐1 blockade therapy." (PMID 31273938, 2019). "Treg cells migrate into the tumor microenvironment where they secrete anti-inflammatory cytokines, inhibit CD4+ T cell proliferation/function, and suppress anti-tumor immune response." (PMID 31394796, 2019). "Neutrophils were named pro-tumor N2 cells or anti-tumor N1 cells after Th1/Th2 CD4 T cells and M1/M2 macrophages." (PMID 31474989, 2019). "Compared with both CAR T cell monotherapy alone and combination therapy, mice treated with anti-PD-1-secreting CAR T cells had a significantly higher ratio of CD8+ versus CD4+ T cells at the tumor site." (PMID 30987642, 2019). "For example, TAM shifts CD4+ T cells from T helper 1 (Th1) to Th2 immunity, and thus, can promote pro-tumor immunosuppression." (PMID 30640711, 2019). "In contrast to CD8+ T cells, there was only a modest but not statistically significant increase in PD-1 expression on CD4+ T cells within the tumor following HER2-DC1 vaccination compared to untreated control." (PMID 31475002, 2019). "Here, we found that both PD-L1 expression in tumor cells and PD-1 expression in tumor-infiltrating CD4+ and CD8+ T cells were increased after TFP treatment in immune-competent mice." (PMID 31572198, 2019). "A typical immune system-escaping strategy employed by tumor cells is inhibiting the Th1 response and recruiting CD4+ CD25+ regulatory T-cells (Tregs)." (PMID 31181729, 2019). "Decreased expression of IL-2 in both CD8+ and CD4+ subsets was connected with the late stage of the neoplasm." (PMID 31582940, 2019). "The results of IF staining show the EpCAM expression and CD4+ T cells distribution in tumor tissues and their para-cancerous tissues of CC patients." (PMID 31354723, 2019). "Immunofluorescence and confocal analyses revealed that, in tumors grown in IL-30KO mice, many of the CD3+T cells expressed TRAIL and that FasL expression mostly co-localized with tumor-infiltrating CD4+T cells." (PMID 31366386, 2019).
tumor (continued). "Profiling of these cells revealed a switch from an immunosuppressive Th2 to a pro-inflammatory Th1 phenotype with increased ratios of INF-y to IL-4 in tumor-infiltrating CD4+ and CD8+ memory T-cells." (PMID 30506500, 2019). "A tumor-specific increase of the CD4+ T-cell response seems more likely to be achieved by CTLA4-blockade than by targeting PD-1, arguing for a combination of PD-L1 and CTLA-4 blockade to reinvigorate the tumor-specific CD4+ T-cell response." (PMID 31481117, 2019). "Of note, a mutation in ERBB2 interacting protein, also recognized by CD4+ T cells, exhibiting a TH1 profile, has been shown effective for mediating tumor regression in a patient with metastatic cholangiocarcinoma treated by adoptive cell transfer." (PMID 31803175, 2019). "Blockade of Runx3 expression sharply increased tumor metastasis, accompanied by fewer tumor-infiltrating CD4+ and CD8+ T cells." (PMID 31122259, 2019). "It was recently shown that MDSCs within brain tumors undergo transmembrane protein programmed death ligand 1 (PD-L1) upregulation, while tumor-derived CD4+ T cells express high levels of PD-1." (PMID 30987226, 2019). "Fewer CD8+ and CD4+ tumor infiltrating lymphocytes (TILs) were found within tumor cell clusters when compared with the stromal compartment in NSCLC." (PMID 31623615, 2019). "Together, these findings place CD4+ T cells as a highly relevant actor in tumor immunity and thus a potential, central prognostic marker for outcome of cancer immunotherapy." (PMID 31754392, 2019). "ANF in combination with PD-L1 blockade exerted potentiated effects in induction of infiltration of CD3, CD8, CD4, and B220 positive cells into tumor tissues, and upregulation of IFNγ and TNFα expression by the lungs." (PMID 30850589, 2019). "Based on the cross-talk between Th2 inflammation and cancers, a recent study shows that tumor progression is promoted by Th2-differentiated CD4+ T cells in response to TSLP." (PMID 31885639, 2019). "Regulatory CD4+ T cells can prevent the differentiation and expansion of cytotoxic T cells as well as DC maturation and therefore prevent tumor elimination." (PMID 30717704, 2019). "CD4+ T cell death is induced by tumor supernatants in a manner that induces ER stress-mediated apoptosis." (PMID 30978945, 2019). "The inhibition of CD4/6-Rb-E2F induces tumor cell-cycle arrest and promotes an anti-tumor immune response through antigen presentation in tumor cells, T-cell activation, and suppression of the proliferation of regulatory T-cells (Tregs)." (PMID 31450618, 2019). "Treatment with RA/CTS polyplexes also increased the population of tumor tissue-infiltrating T cells, producing the highest percentage of CD4(+) and CD8(+) T cells." (PMID 31847372, 2019). "Among CD4+ T cells present in the tumor, a subset of CD4+CD25highFoxp3+ Treg cells are able to suppress proliferation of other T cells within the microenvironment through contact-dependent mechanisms, or anti-inflammatory cytokine (IL-10 and TGFβ) secretion." (PMID 31430935, 2019). "Regulatory T cells are a subset of CD4+ T cells with immunosuppression that influence tumor immunotherapy and vaccine activation." (PMID 31365790, 2019). "Combination therapy resulted in an increase in the percentage of tumor-infiltrating CD4+ T cells, compared to anti-4-1BB." (PMID 30635578, 2019). "Unlike Tregs, surface expression of CTLA-4 by both naïve and anti-tumor CD4+ and CD8+ effector memory T cells only occurs following major histocompatibility complex (MHC)-dependent activation of these cells by APCs." (PMID 31616428, 2019). "The current notion of the opposing nature of immune cells in tumors is that CD8+ T cells, CD4+ Th1 cells, NK cells, B cells, classically activated macrophages (M1), and mature dendritic cells contribute to tumor elimination." (PMID 31366131, 2019).